IKBKE (inhibitor of nuclear factor kappa B kinase subunit epsilon)
Diseases named in the same sentence as IKBKE in open-access papers (continued):
Sharing a sentence is not in itself a finding about the gene and the disease.
tumor (56 papers, 2010 to 2026). "For example, JQ1 and I-BET151 exert anti-cancer functions by reducing IKBKE expression to block the NF-κB signaling pathway, although tumor-associated macrophages in TNBC confound this effect by increasing IL-6 or IL-10/STAT3/IKBKE/NF-κB axis." (PMID 34595180, 2021). "IKBKE is increased in several types of cancers and is associated with tumour malignancy." (PMID 28548934, 2017). "Genes such as BRCA1, CHEK2, and IKBKE are significantly upregulated in tumor tissues and serve as prognostic risk factors for GBM patients, suggesting that these genes may promote the initiation and progression of GBM by promoting neoplastic cell multiplication and impeding programed cell death." (PMID 41497799, 2025). "We calculated the ratio of IKBKE expression in each tumor compared with adjacent normal tissue and plotted the data by cancer type." (PMID 41542764, 2026). "Treatment with amlexanox markedly suppressed tumor growth and synergized with GEM to enhance anti-tumor efficacy in organoid models by targeting IKBKE." (PMID 41699675, 2026). "The therapeutic potential of IKBKE targeting was further validated using patient-derived tumor organoids and xenograft models." (PMID 41699675, 2026). "MATERIALS AND METHODS: We examined IKBKE expression in patient tumor tissues and publicly available databases and assessed its prognostic value to investigate its function in PDAC chemoresistance." (PMID 41699675, 2026). "IKBKE knockdown suppresses tumor growth and reduces autophagy, highlighting its role in autophagy-mediated progestin resistance." (PMID 41378297, 2025). "Consistently, our findings indicate that IKBKE knockdown reduces proliferation and migration in progestin-resistant EC cells, highlighting its role in sustaining drug resistance and tumor progression." (PMID 41378297, 2025). "Among the eight significant mutated genes, CDK12, CTNNB1, and MLH1 were tested in both tumor and blood, whereas CTCF, IGF1R, IKBKE, QKI, and TIPARP were only tested in tDNA." (PMID 40227722, 2025). "By contrast, the atypical inflammatory kinase IKBKE was significantly enriched in the immune subgroup 327,28, which has been reported to promote PCa tumor growth through modulating the Hippo pathway." (PMID 40180929, 2025). "The correlation of IKBKE expression with clinical tumor staging was evaluated based on the TCGA-KIRC database." (PMID 39664571, 2024). "The effects of IKBKE silencing on MAPK activation in tumor vs. normal cells were evaluated via WB and RT-PCR." (PMID 35391917, 2022). "Recent studies have showed that IKBKE is overexpressed in several kinds of cancers and that IKBKE-knockdown inhibits tumor progression." (PMID 34544426, 2021). "Combining IKBKE small molecule inhibitors with MEK inhibitors significantly inhibited the xenograft tumor growth of NSCLC in vivo." (PMID 31733040, 2020). "Generally, IKBKE plays an important role in tumorigenesis, antichemotherapeutic properties, tumor metastasis and tumor microenvironment." (PMID 31733040, 2020). "Targeting IKBKE with small molecule inhibitors in both PC cell line xenografts and patient ex vivo explant models resulted in reduced tumour volume, inhibition of proliferation and reduced AR expression." (PMID 32324216, 2020). "We next explored the therapeutic potential of IKBKE antagonism using CYT387 in a system that more closely recapitulates human tumour physiology using patient-derived prostate tissue explants." (PMID 32324216, 2020). "These conclusions suggested that IKBKE supported tumor growth through favouring the chronic inflammation microenvironment, which was necessary for tumor development." (PMID 31733040, 2020). "Intracranial tumours transfected with IKBKE-shRNA were significantly smaller than those infected with scrambled lentivirus." (PMID 28548934, 2017). "Therefore, CYT387 has also been identified as a potent IKBKE inhibitor that effectively blocks NF-κB-driven tumor proliferation, survival, and immunomodulation." (PMID 41378297, 2025).
tumor (continued). "In addition to its role in inhibiting JAK/STAT signaling, preclinical studies demonstrated the efficacy of CYT387 in triple-negative breast cancer, where it suppressed tumor growth by inhibiting IKBKE-induced NF-κB and STAT activation." (PMID 41378297, 2025). "There was a notable divergence in gene expression levels between neoplastic and neighboring tissues, with genes such as BRCA1, CHEK2, and IKBKE substantially amplified in tumor tissues, while genes such as ZMYND11, MAPK8, and RPS3 exhibited notable elevation in adjacent nontumor tissues." (PMID 41497799, 2025). "Notably, IKBKE expression showed a strong positive correlation with tumor stage, including TNM stage and tumor grade by the Mann-Whitney U test." (PMID 39664571, 2024). "However, IKBKE exhibited lower methylation levels in tumor samples, whereas TBK1 showed higher methylation levels in tumor samples compared to normal samples." (PMID 38817870, 2024). "Accumulating evidence support that IKBKE orchestrate tumor cell survival in cancers." (PMID 35391917, 2022). "Since IKBKE has become an increasingly important therapeutic target for numerous malignancies, a series of microRNAs have been identified as vital regulators to control the expression of IKBKE, thus promoting tumor progression." (PMID 31733040, 2020). "Additionally, YAP1 and TEAD2, two vital Hippo pathway downstream transcription factors, obviously decreased in IKBKE-silenced tumour cells, suggesting that the reversed EMT process caused by IKBKE downregulation was likely regulated by the Hippo pathway." (PMID 28548934, 2017). "Furthermore, we stained the intracranial tumours with IKBKE, YAP1, MMP-2, MMP-9, E-cadherin, N-cadherin, β-catenin, vimentin, and snail." (PMID 28548934, 2017). "Indeed, we show that knockdown and inhibition of IKBKE can reduce proliferation, migratory ability and tumour volume supporting our hypothesis that IKBKE inhibition is a viable clinical strategy." (PMID 32324216, 2020). "Then, we further discovered that IKBKE increased Yes-associated protein 1 (YAP1) and TEA domain family member 2 (TEAD2), two important Hippo pathway downstream factors, to induce an epithelial–mesenchymal transition (EMT), thus contributing to tumour invasion and metastasis." (PMID 28548934, 2017). "IKBKE targeting reverses GEM resistance and enhances tumor immunogenic cell death via the caspase-3/GSDME pathway, supporting IKBKE inhibition as a promising therapeutic strategy for PDAC." (PMID 41699675, 2026). "The IKBKE/TBK1 inhibitor, Amlexanox, can repress cancer cell proliferation and invasion and has shown efficacy in different experimental tumor models." (PMID 40468448, 2025). "No in vivo experiments, such as subcutaneous xenografts, were performed to evaluate the effects of IKBKE knockdown on tumor growth, pharmacological response, or Ki-67/LC3-II expression in tumor tissues." (PMID 41378297, 2025). "In essence, our comprehensive correlation analysis underscores the profound connection between IKBKE, HSPA1A, and immune cell infiltration in the LIHC tumor microenvironment." (PMID 39000042, 2024). "We are eager to delve deeper into the single-cell expression patterns of IKBKE and HSPA1A in LIHC, with the ultimate goal of unraveling their precise functions within distinct immune cell subpopulations of the tumor microenvironment." (PMID 39000042, 2024). "In this study, we demonstrated that IKBKE was upregulated in RCC, and its high expression was correlated with advanced tumor staging and poor prognosis." (PMID 39664571, 2024). "Moving forward, we delve into the complex relationship between IKBKE, HSPA1A, and immune infiltration in LIHC, shedding light on the intricate interactions within the tumor microenvironment and paving the way for more targeted therapeutic approaches." (PMID 39000042, 2024). "Alterations in the expression of DDX58, MAVS, C6orf150, TMEM173, IKBKE, TBK1 and IRF3 were analyzed across different tumor samples using cBioPortal." (PMID 38817870, 2024).
tumor (continued). "This upregulation suggests a potential role for IKBKE in the activation, proliferation, or regulatory functions of these immune cell subsets within the LIHC tumor microenvironment." (PMID 39000042, 2024). "Afterwards, we delved into the validation of IKBKE and HSPA1A expression in LIHC, elucidating their potential role in the tumor microenvironment of LIHC." (PMID 39000042, 2024). "Collectively, our findings at the single-cell level strongly implicate IKBKE and HSPA1A in the regulation of local immune responses and the modulation of the tumor microenvironment in LIHC." (PMID 39000042, 2024). "PPI network analysis revealed these genes and modules were mainly related to tumor progression (LOXL1, IKBKE, LNX1, FOXA2, FGF17, and FGF2) and immune response (STAT4, IL23R, LTA, ITK, and IL19)." (PMID 36611170, 2023). "We describe here a novel regulatory link between IKBKE and constitutive ERK1/2 activation in tumor cells." (PMID 35391917, 2022). "Generally, CYT387 can inhibit both IKBKE activation and JAK/STAT activation to regulate tumor growth via a complicated pathway." (PMID 34544426, 2021). "Zubair et al39 demonstrated that silencing of IKBKE in PDAC cell lines inhibited the proliferation of tumor cells and the number of colony forming cells and reduced the glucose uptake of tumor cells." (PMID 31733040, 2020). "Challa et al56 found high expression of IKBKE in several NSCLC cell lines and silencing of IKBKE decreased tumor cell proliferation, colony growth and invasion in vitro." (PMID 31733040, 2020). "This analysis indicated that both IKBKE and PSAT1, similarly to PHGDH and PSPH, are significantly upregulated in an ER‐negative Pam50:basal subpopulation of tumours, with the highest proliferation index." (PMID 32783398, 2020). "The efficacy of IKBKE pharmacological antagonism in vivo was tested using the Phase III, dual IKBKE/JAK2 antagonist, CYT387, on CWR22Rv1 tumour xenograft growth." (PMID 32324216, 2020). "Both inhibitor of nuclear factor kappa B kinase subunit epsilon (IKBKE) and Jumonji domain-containing 6 (JMJD6) contribute to enhancement of tumor supportive autophagy." (PMID 32878084, 2020). "As expected, treatment with anti–PD-1 antibody, IR, or IKBKE-e ASO alone did not result in a substantial reduction in tumor growth, recapitulating the failure of immunotherapy, IR, or ARPI alone in CRPC observed in multiple clinical trials." (PMID 41542764, 2026). "As a member of the noncanonical IκB kinase family, inhibitor of nuclear factor kappa-B kinase subunit epsilon (IKBKE) is known to regulate tumor progression in multiple cancer types." (PMID 41699675, 2026). "Furthermore, IKBKE has been shown to activate the AKT pathway, which plays an important role in tumor progression and chemotherapy resistance 30-32." (PMID 39664571, 2024). "To gain a more precise understanding of the expression patterns of IKBKE and HSPA1A in different immune cell and cancer cell subpopulations, as well as their potential roles within the tumor microenvironment, we explored their expression in LIHC using single-cell transcriptomic analysis." (PMID 39000042, 2024). "Furthermore, our q-PCR results revealed a substantial increase in the transcription levels of IKBKE and HSPA1A in LIHC tumor tissues compared to adjacent normal tissues." (PMID 39000042, 2024). "For in vitro studies, the role of IKBKE, IGF1R, NOTCH3 and MDM4 in tumorigenesis and tumour metastasis have been reported and have provided clinicians with potential insights for understanding the biological behaviour of TNBC and exploring treatment strategies for heavily treated patients." (PMID 34396843, 2021). "Whilst this requires further investigation, there is also scope to investigate the utility of IKBKE targeting therapeutics in highly aggressive AR negative tumours." (PMID 32324216, 2020). "In vivo results further confirmed the tumor inhibitory effect of amlexanox via the downregulation of IKBKE, and amlexanox induced no apparent toxicity." (PMID 29048430, 2017).
tumor (continued). "Initially, we examined the expression levels of key genes within the innate immune pathway, namely DDX58, MAVS, C6orf150, TMEM173, IKBKE, TBK1 and IRF3, across diverse tumor and non-tumor tissues." (PMID 38817870, 2024). "Our findings indicated that DDX58, MAVS, C6orf150, IKBKE, TBK1, and IRF3 expression were not significantly correlated with tumor purity." (PMID 38817870, 2024).
cancer (53 papers, 2012 to 2026). A tumor composed of atypical neoplastic, often pleomorphic cells that invade other tissues. "IKBKE, an oncogenic kinase implicated in various cancers, including breast, ovarian, and prostate, has an unclear role in autophagy regulation and progestin resistance in EC." (PMID 41378297, 2025). "The kinase ΙΚΚε (encoded by IKBKE gene) has been shown to be an oncogene in breast and ovarian cancers." (PMID 29801480, 2018). "IKBKE has been identified as a key regulator of autophagy in various cancer models, modulating vesicle formation and autophagy-related proteins such as Beclin-1 and LC3 through its aberrant expression." (PMID 41378297, 2025). "The anti-cancer effects of Amlexanox have been attributed to the inhibition of IKBKE and TBK1 but also to the inhibition of other proteins like FGF-1 and S100 proteins." (PMID 40468448, 2025). "IKBKE inhibition disrupts autophagy, leading to reduced cancer cell proliferation and increased apoptosis." (PMID 41378297, 2025). "IKBKE is an atypical inflammatory kinase that is a key regulator of the immune system, inflammation, and cancer." (PMID 38757752, 2024). "PTPRU, IKBKE, STYK1, and CENPO are implicated in key biological pathways relevant to cancer biology, including cell signaling, cell migration, and inflammation, further supporting their relevance in tumorigenesis." (PMID 39684488, 2024). "Increasing evidence has demonstrated a strong correlation between inhibitor of nuclear factor kappa B kinase subunit epsilon (IKBKE) and cancer progression as well as drug resistance." (PMID 39664571, 2024). "IKBKE plays a crucial role in the regulation of inflammatory response and immune cells, and the pathogenesis of malignant tumors." (PMID 38900330, 2024). "Recent studies have shown that IKBKE is highly expressed in a variety of malignant tumors, and the difference in expression is related to the prognosis of patients." (PMID 31733040, 2020). "As the regulatory mechanism of IKBKE in tumors has gradually been revealed in recent years, its critical role in tumorigenesis and development of malignant tumors has been increasingly recognized." (PMID 31733040, 2020). "In several cancers, IKBKE has been demonstrated to be amplified and overexpressed moreover, it has been found to be oncogenic in breast and ovarian cancer." (PMID 32324216, 2020). "Recent studies have demonstrated that IKBKE plays a crucial regulatory role in malignant tumor development." (PMID 31733040, 2020). "Colas et al47 analyzed 52 carcinoma samples using gene expression screening and found that IKBKE was overexpressed in EC (endometrial carcinoma)." (PMID 31733040, 2020). "Downregulation of the IKBKE gene was previously reported to attenuate CCL2 release that led to cancer cell death." (PMID 30059519, 2018). "Increasing evidence suggests that IKBKE is overexpressed in numerous malignancies 24-26, and its overexpression has been correlated with the proliferation, invasion, and metastasis of various cancers 27-29." (PMID 39664571, 2024). "IKBKE was dramatically upregulated in various types of cancer, including RCC." (PMID 39664571, 2024). "As a result, IKBKE have emerged as potential target for cancer therapy." (PMID 35391917, 2022). "The activation of IKBKE could facilitate cell transformation; suppression of IKBKE in cancer cell lines with IKBKE overexpression results in cell death." (PMID 36726781, 2022). "Recent studies have shown that IKBKE dominates cancer progression induced by the NF-κB pathway." (PMID 34544426, 2021). "One of the most recent studies published in this field describes co-delivery of siRNA against triple-negative breast cancer oncogene IKBKE (Inhibitor of nuclear factor kappa-B kinase subunit epsilon) and cabazitaxel in nanocomplex modified with hyaluronic acid-targeting cancer cells." (PMID 33802861, 2021).
cancer (continued). "Furthermore, with IKBKE levels elevated in cancers, including PC, aberrant IKBKE activity offers another explanation as to why LATS protein levels are down-regulated in cancers." (PMID 33557087, 2021). "Interestingly, in PC, IKBKE exhibits elevated protein expression in cancers compared to normal cells." (PMID 32324216, 2020). "Taken together these results suggest that diminishing IKBKE signalling in PC cells may prove therapeutically beneficial for patients by suppressing AR signalling to prevent cancer cell growth and metastases." (PMID 32324216, 2020). "IKBKE promotes the growth, proliferation, invasion, and drug resistance of various cancers." (PMID 31733040, 2020). "Consequently, silencing IKBKE has been reported to reduce the NF-κB activity and inhibit proliferation, clonogenicity, angiogenesis, migration, invasion, and metastasis in BC cells and many other cancer types." (PMID 35955463, 2022). "In addition, Adli et al65 demonstrated that IKBKE was highly expressed in multiple cancer cells, directly phosphorylates p65 at the serine 536 site to enhance NF‐κB transactivation and then promoted the proliferation of cancer cells." (PMID 31733040, 2020). "Using quantitative PCR, we quantified IKKε (IKBKE) and TBK1 mRNA via normalization to a GUSB internal control in different KRAS mutant cancer cells." (PMID 40738190, 2025). "Among these, PLXNA3, HLA-E, DDX58, IKBKE, HSPA6, SOS2, and HSPA1A stood out, with significantly elevated expression levels in LIHC compared to other cancer types." (PMID 39000042, 2024). "In terms of gene expression, SPP1, IKBKE, CXCL11, CXCL10, and other genes showed extensive high expression in COAD, ESCA, KIRC, READ, UCEC, and other cancers." (PMID 37666853, 2023). "Wu et al67 demonstrated that miR‐200b downregulates IKBKE expression via directly binding to its 3ʹ‐UTR, thus suppressing NF‐κB activation to inhibit cancer progression." (PMID 31733040, 2020). "According to the data, numerous genes (such as H2AFX, CDKN2A, TTF2, IKBKE, and UBE2I) were markedly upregulated in many cancer types, while some genes (such as ARRB1, LMO3, KHDRBS2, CIRBP, and RALYL) were remarkably downregulated in multiple cancer types." (PMID 35003212, 2021). "Recent studies demonstrated that IKBKE, as an IKK family protein factor, plays an important regulatory role not only in the activation of inflammatory factors and the progression of metabolic diseases and cellular immunity but also in the development of various malignant tumors." (PMID 31733040, 2020). "Almost in all transformed or cancer cell lines we examined, we observed a reduced ERK1/2 baseline or constitutive phosphorylations in the absence of IKBKE." (PMID 35391917, 2022).